BRF2 (BRF2 general transcription factor IIIB subunit)
Description:
General activator of RNA polymerase III transcription. Factor exclusively required for RNA polymerase III transcription of genes with promoter elements upstream of the initiation sites. Contributes to the regulation of gene expression; functions as activator in the absence of oxidative stress. Down-regulates expression of target genes in response to oxidative stress. Overexpression protects cells against apoptosis in response to oxidative stress.
Synonyms: TFIIIB50; BRFU; FLJ11052
Tractability: Small molecule: a structure with a bound ligand is known. PROTAC: ubiquitination databases record sites on it.
Gene: Protein-coding gene on chromosome 8 (37,843,268 to 37,849,861, reverse strand). Ensembl gene ENSG00000104221.
Subcellular location: Nucleus
Subcellular location (Human Protein Atlas): Nucleoli
Pathways (Reactome):
Gene expression (Transcription): RNA Polymerase III Abortive And Retractive Initiation; RNA Polymerase III Transcription Initiation From Type 3 Promoter
Gene Ontology:
Molecular function: protein binding; RNA polymerase III type 3 promoter sequence-specific DNA binding; RNA polymerase II general transcription initiation factor activity; TBP-class protein binding
Biological process: cellular response to oxidative stress; positive regulation of transcription by RNA polymerase III; regulation of transcription by RNA polymerase III; DNA-templated transcription initiation; transcription by RNA polymerase II; transcription preinitiation complex assembly
Cellular component: nucleolus; transcription factor TFIIIB complex; nucleoplasm; nucleus; transcription preinitiation complex
Genetic constraint (gnomAD): Loss-of-function variants: 17 observed, 30.82 expected, observed/expected ratio (o/e) 0.55, 90% interval 0.38 to 0.83. The upper end of that interval is the gene's LOEUF score, 0.83, which puts it in group 3 of 6, group 1 being the genes least tolerant of losing a copy. Missense variants: 515 observed, 565.8 expected, observed/expected ratio (o/e) 0.91, 90% interval 0.85 to 0.98. Synonymous variants: 219 observed, 239.71 expected, observed/expected ratio (o/e) 0.91, 90% interval 0.82 to 1.02.
Homologues: Orthologues: chimpanzee BRF2 (100% identical), macaque BRF2 (98% identical), pig BRF2 (90% identical), dog BRF2 (89% identical), rabbit BRF2 (87% identical), guinea pig BRF2 (86% identical), rat Brf2 (85% identical), mouse Brf2 (83% identical), tropical clawed frog brf2 (50% identical), zebrafish brf2 (34% identical). Paralogues in human: BRF1 (20% identical), GTF2B (16% identical).
Diseases named in the same sentence as BRF2 in open-access papers:
BRF2 is named in the same sentence as 44 diseases in open-access papers, as found by Europe PMC text mining. Sharing a sentence is not in itself a finding about the gene and the disease. The quoted sentences say what the papers report.
lung carcinoma (18 papers, 2010 to 2025). "Silencing of BRF2 in lung cancer cells inhibits cell proliferation and migration, while promoting cell apoptosis." (PMID 40229899, 2025). "Recent studies have shown that BRF2 is overexpressed in various solid cancers, including lung cancer, breast cancer, and esophageal squamous cell cancer." (PMID 37653482, 2023). "BRF2 upregulation has been observed in many types of cancers and is critical in the development and progression of various cancers, including lung cancer, breast cancer, and esophageal squamous cell cancer." (PMID 37653482, 2023). "One study used the Oncomine database to study the expression of BF2 in tumors in a subset of the patient samples and showed that BRF2 is both over‐ and under‐expressed in lung cancer." (PMID 35293140, 2022). "Studies have shown high basal levels of BRF2 expression in breast and lung cancers, where it is a potential independent prognostic factor for the recurrence and metastasis of lung cancer." (PMID 34359683, 2021). "Studies have shown a high basal level of BRF2 expression in breast and lung cancer, as well as in cancer cell lines such as HCC95 which are subjected to prolonged oxidative stress." (PMID 34359683, 2021). "BRF2 was identified as a lineage-specific marker in lung cancer and was later recognized as an oncogenic driver in breast cancer and esophageal carcinoma." (PMID 34359683, 2021). "So we conclude that BRF2 possesses a certain effect in invasion and metastasis of lung cancer and is an independent prognostic factor of recurrence and metastasis in lung cancer." (PMID 24738062, 2014). "The data retrieved from the Garber Lung study shows a correlation between BRF2 overexpression and an advanced N stage, N1, in lung carcinoma samples." (PMID 21518452, 2011). "In lung cancer, pathways upregulating BRF2 have been shown to favor cancer progression." (PMID 36902501, 2023). "MNX1-AS1 drove lung cancer growth and metastasis using the miR-527/BRF2 pathway." (PMID 33882027, 2021). "Previously, BRF2 expression in human cancers using the Oncomine 3.0 database analyzed transcriptome data across 18,000 gene expression microarrays and 35 cancer subtypes and identified BRF2 overexpression in patients with gastric, kidney, melanoma, and lung cancers." (PMID 33176745, 2020). "Whether targeting of BRF2 is a potential mechanism of miR-425-5paffecting the lung cancer cell growth?" (PMID 31964245, 2020). "Then, we furtherdeciphered that miR-425-5p may inhibit lung cancer cell growth and tumor growth by targetingand downregulating BRF2, which was identified as a new mechanism of microRNA inhibit lungcancer." (PMID 31964245, 2020). "In both breast and lung cancers, the BRF2 gene is amplified and overexpressed and may serve as an oncogenic driver." (PMID 26573593, 2015). "To find out whether BRF2 mediates prognosis in lung cancer through promoting metastasis, we applied small interfering RNA technology to knock down the BRF2 expression on the migratory and invasive ability of A549 and SK-MES-1 cells." (PMID 24738062, 2014). "Therefore, it is essential to further investigate the functional role of BRF2 in lung cancer invasion and metastasis." (PMID 24738062, 2014). "To investigate whether BRF2 regulates the EMT transition in lung cancer cells, we examined the expression of the key EMT markers E cadherin and N-cadherin in BRF2 knocked down lung cancer cells by western blotting analysis." (PMID 24738062, 2014). "The expression of BRF2 in lung cancer, adjacent lung cancer tissues and normal lung tissues." (PMID 24523874, 2014). "For example, BRF2, which we recently identified as a lineage specific oncogene in lung SqCC, was deregulated in this manner, highlighting its importance to the development of this lung cancer subtype." (PMID 22629454, 2012). "Moreover, miR-527 has been shown to inhibit lung cancer progression by interacting with BRF2." (PMID 35210429, 2022).
lung carcinoma (continued). "BRF2 expression was found to be facilitated by MNX1-AS1/miR-527 axis and contributed to lung cancer development." (PMID 33472586, 2021). "In lung cancer, MNX1-AS1 was capable of promoting tumor cell proliferation, mobility, and invasion by regulating the miR-527/BRF2 signaling axis." (PMID 33685348, 2021). "In addition, miR-527 was identified to suppress lung cancer cell proliferation and migration through targeting TFIIB-related factor 2 (BRF2), an oncogene that is critical for Pol III recruitment and transcription initiation." (PMID 33472586, 2021). "Moreover, we demonstrated for the first time that BRF2 promotes cell metastatic and invasive capacities by inducing EMT phenotype in lung cancer cells." (PMID 24738062, 2014). "As expected, assessment of transcript levels in the lung cancer lines showed drastically higher levels of both U6 and 7SK relative to 5S loading control in H520 cells compared to H1395 and H2347 cells, confirming increased BRF2-dependent Pol III transcription upon BRF2 activation." (PMID 20668658, 2010).
breast carcinoma (16 papers, 2007 to 2025). "We identified BRF2 as a potential cis-associated driver gene in breast cancer by performing copy-number-altered network analysis." (PMID 34359683, 2021). "The BRF2 gene that is implicated in cancer can be induced in human breast cancer cells by the isoflavone daidzein, through promoter demethylation and/or mRNA stabilization." (PMID 26573593, 2015). "In addition, we identified and functionally validated alternative driver genetic alterations restricted to the HER2-negative component of HER2 heterogeneous breast cancers, including BRF2 and DSN1 amplification, and a HER2 somatic mutation." (PMID 25994018, 2015). "However, its amplification is mutually exclusive to DNA repair defects in breast cancer, suggesting that overexpression of BRF2 may result in DNA damage repair deficiencies." (PMID 34359683, 2021). "In prostate cancer and breast cancer with high expression of BRF2, pan-active BCL-2 protein family antagonist (Sabutoclax) inhibits tumor progression by promoting cell apoptosis." (PMID 40610422, 2025). "We have previously shown that BRF2 is upregulated in several breast cancer cell lines compared to near-normal mammary epithelial lines, and breast cancer cell lines with high BRF2 expression are dependent on it for cellular viability." (PMID 34359683, 2021). "We and others have shown a context-dependent role of BRF2 as a cis-associated ‘alternative driver oncogene’ with a significant role in lung and ER−/HER2+ breast cancers, respectively." (PMID 34359683, 2021). "The analysis of 180 patients and 237 samples from the Metastatic Breast Cancer Project revealed that 32% of metastatic breast cancers exhibited amplification and upregulation of BRF2." (PMID 34359683, 2021). "This analysis suggests that BRF2 is a potential therapeutic target in multiple cancers, including breast cancer." (PMID 34359683, 2021). "First, we found a negative correlation between the drug sensitivity and the expression of BRF2 in breast cancer cell lines, which indicates that this drug is more efficient when BRF2 expression is higher." (PMID 34359683, 2021). "This is supported by our in vitro data in human breast cancer lines, showing that BRF2 protein levels are regulated after the exposure of cells to DNA-damaging agents, rather than at the transcript level." (PMID 34359683, 2021). "The IC50 of Bex correlated negatively to the expression of BRF2 among the breast cancer cell lines (the threshold of expression set to −2 to 2), unlike the other available drugs on the list (alectinib and AZD5991)." (PMID 34359683, 2021). "The mutual exclusivity of BRF2 amplification and BRCA1/2 loss was also observed in breast cancer cell lines in the CCLE database." (PMID 34359683, 2021). "In this study, we performed a meta-analysis of patient data from both Oncomine and cBioPortal databases to analyze BRF2 alterations in human cancers, with a focus on breast cancer." (PMID 33176745, 2020). "Using the Oncomine Power Tools, we determined the frequency of BRF2 of overexpression to be highest in breast cancers (2.0%) as compared to lung (1.1%) cancer where BRF2 has been identified as a novel lineage-specific oncogene in lung squamous cell carcinoma." (PMID 33176745, 2020). "Next, we compared BRF2 overall survival status results with known oncogenes and biomarkers in breast cancer by analyzing the same data set for ERBB2 (HER2), ESR1 (ER), and PIK3CA." (PMID 33176745, 2020). "Under these highly stringent selection criterion, the Outlier analysis returned 8 breast cancer data sets where BRF2 is significantly overexpressed." (PMID 33176745, 2020). "BRF2 is specifically overexpressed in 36 of 60 (60%) and underexpressed in 4 of 60 (0.07%) of breast cancer data sets analyzed." (PMID 33176745, 2020). "BRF2 copy number events occur most frequently in breast cancer, 5.9%, as compared to other human cancers analyzed." (PMID 33176745, 2020).
breast carcinoma (continued). "Together, studies regarding BRF2 expression and chemotherapeutic agents working through the ER are necessary in the context of breast cancer." (PMID 33176745, 2020). "The outlier analysis identified HER2 as overexpressed in 33 breast cancer data sets and ESR1 as overexpressed in 3 breast cancer data sets whereas BRF2 is overexpressed in 8 breast cancer data sets." (PMID 33176745, 2020). "Next, we compared the BRF2 Outlier results to known breast cancer biomarkers, HER2 (ERBB2), MYC, PIK3CA, and ER (ESR1) using the same stringent threshold criterion." (PMID 33176745, 2020). "Outlier analyses of the Oncomine microarray data suggest BRF2 is a novel outlier gene in breast cancer." (PMID 33176745, 2020). "Chromosome 8 is frequently amplified in human breast cancer cell lines and BRF2, located on chromosome 8p11.23, has been demonstrated to be amplified in breast cancer and identified as a potential oncogenic driver in breast cancer." (PMID 33176745, 2020). "A meta cancer outlier profile analysis (COPA) of 715 data sets (86,733 samples) in Oncomine identified BRF2 as overexpressed in 60% of breast cancer data sets." (PMID 33176745, 2020). "Using the cBioPortal we queried for BRF2 alteration in the two available metastatic breast cancer data sets: Metastatic Breast Cancer (INSERM, PLoS Med 2016) and the Metastatic Breast Cancer Project (Provisional, October 2018)." (PMID 33176745, 2020). "The cytogenetic location of BRF2 is 8p11.23 and amplification of the short arm of chromosome 8 is a frequent feature of breast cancer cell lines and tumors." (PMID 33176745, 2020). "Of the Oncomine breast cancer data sets available for analysis, 2.0% have an increased frequency of BRF2 expression and ductal carcinoma had the highest BRF2 overexpression frequency." (PMID 33176745, 2020). "In this study, we demonstrate that BRF2 is amplified in 5.9% of all breast cancers and 6.9% of all ductal breast carcinomas queried." (PMID 33176745, 2020). "The observed statistically significant overexpression of BRF2 in intraductal cribriform breast adenocarcinoma, p = 9.34E-7, prompted a more detailed look at BRF2 alterations in subtypes of breast cancer." (PMID 33176745, 2020). "A larger study of BRF2 alterations and ER status in breast cancer is needed to determine correlative value." (PMID 33176745, 2020). "Taken together, these data highlight the need to investigate BRF2 copy number and overall patient survival in breast cancer in greater detail." (PMID 33176745, 2020). "Together, these data suggest the observed BRF2 overexpression in breast cancer warrant a more detailed investigation to determine if BRF2 alterations correlate with clinical outcomes." (PMID 33176745, 2020). "BRF2 is a known oncogene in both breast cancer and lung squamous cell carcinoma, and a core RNA polymerase III transcription factor that senses and reacts to cellular oxidative stress." (PMID 27145341, 2016). "The BRF2 subunit of TFIIIB is encoded by an oncogene at 8p12 that is frequently amplified and overexpressed in breast cancers and lung squamous cell carcinomas (SqCC)." (PMID 26573593, 2015). "BRF2 (8p11.23) maps to the 8p11-p12 amplicon and is reported to be recurrently amplified in 10 to 15% of breast cancers." (PMID 25994018, 2015). "Detailed genomic analyses of these components coupled with in vitro experiments resulted in the identification of BRF2 and DSN1 amplification and HER2 I767M somatic mutation as potential novel breast cancer driver genetic events." (PMID 25994018, 2015). "Amplification of BRF2 has been noted in breast cancer and more recently a human bladder cancer cell line." (PMID 21518452, 2011). "Analysis of the 95% outlier across 17 breast carcinoma analyses shows that BRF2 is highly overexpressed." (PMID 21518452, 2011). "BRF2 has also been recognized as an oncogenic driver in breast cancer." (PMID 36927769, 2023).
breast carcinoma (continued). "Additionally, BRF2 has been shown to play a crucial role in breast cancers with heterogeneous HER2 gene amplification." (PMID 34359683, 2021). "We also discovered the regulation of BRF2 after DNA damage in breast cancer." (PMID 34359683, 2021). "The phytoestrogen daidzein induces BRF2 mRNA in breast cancer cell lines and a mouse model." (PMID 33176745, 2020). "In addition, BRF2 is significantly overexpressed in the TCGA Breast Cancer data set, n = 593 samples and p = 9.34E-7." (PMID 33176745, 2020). "Amplification of BRF2, 8p11.23, and chromosome 8 frequently occurs in somatic breast cancer." (PMID 33176745, 2020). "BRF2 has been determined to be overexpressed in a subset of human cancers, but BRF2 alterations have never been investigated to correlate with clinical outcomes in breast cancer." (PMID 33176745, 2020). "However, a separate query of the Breast Cancer METABRIC data set in the cBioPortal for BRF2 alterations and overall survival was correlative." (PMID 33176745, 2020). "In this context, ectopic overexpression of Brf2 in lung fibroblasts and mammary epithelial cells reveals Brf2 oncogenic potential under oxidative stress conditions, supporting its role as an oncogenic driver in lung squamous cell carcinoma and breast cancer." (PMID 26638071, 2015). "BRF2 overexpression may also be an oncogenic driver in some breast cancers and human mammary epithelial cells can be transformed by transfection of the BRF2 gene." (PMID 26573593, 2015). "Since Brf2 has been recently discovered as a top-scoring candidate driver in breast carcinomas, we additionally investigated the effects of Brf2 overexpression on selenoproteins expression levels and evasion of apoptosis in MCF10A cells, a mammary epithelium cell line with low expression of Brf2." (PMID 26638071, 2015). "Based on the BRF2 disease summary, we focused on breast carcinoma as this was most significant." (PMID 21518452, 2011). "Furthermore, we evaluated BRF2 as a potential prognostic biomarker in breast cancer." (PMID 33176745, 2020). "However, correlations between BRF2 alterations and clinical outcomes in breast cancer are limited." (PMID 33176745, 2020). "Furthermore, we establish Brf2 as a central redox-sensing transcription factor involved in the oxidative stress pathway and provide a mechanistic model for Brf2 genetic activation in lung and breast cancer." (PMID 26638071, 2015). "Hence, we speculate that since Brf2 has been shown to be amplified in breast cancers and has been proposed to be a candidate oncogene, strict regulation of Brf2 expression could be critical in preventing the oncogenic phenotype." (PMID 18700021, 2008). "The overexpression of BRF2, a selective subunit of RNA polymerase III, has been shown to be crucial in the development of several types of cancers, including breast cancer and lung squamous cell carcinoma." (PMID 34359683, 2021). "Together, the median gene rank and COPA scores for BRF2 and HER2 are comparable in the meta-analysis of 3594 breast cancer patients included in this analysis." (PMID 33176745, 2020). "Using the same stringent threshold criteria used in the outlier analysis for BRF2 an outlier analysis of TFIIB demonstrated TFIIB overexpression in 5 of 67 (0.07%) and TFIIB underexpression in 17 of 67 (25%) breast cancer data sets analyzed." (PMID 33176745, 2020). "Using the results from the Outlier analyses for BRF2 we analyzed BRF2 across outlier breast cancer data sets with greater than 1000 samples and restricted the analysis to the 95th percentile to determine median gene rank and COPA score for BRF2." (PMID 33176745, 2020). "The cytogenetic locations of BRF2 (8p11.23) and MYC (8q24.21) are on a portion of chromosome 8 known to be amplified in breast cancer." (PMID 33176745, 2020).